RAG1 (recombination activating 1)
Diseases named in the same sentence as RAG1 in open-access papers (continued):
Sharing a sentence is not in itself a finding about the gene and the disease.
colitis (continued). "We reasoned that in such a model the induction of colitis with effector T cells without the presence of Tregs in Nlrp3R258Wx Rag1−/− mice could abrogate the protective function of remodelled microbiota, and lead to greater severity of disease given that the mutation is pro-inflammatory." (PMID 29196621, 2017). "C57BL/6 Rag1−/− mice adoptively transferred with HDAC10−/− but not wild Treg, were protected from developing colitis." (PMID 31949209, 2020). "Intriguingly, in contrast to the anti-CD40 model of colitis, depletion of ILC in the Rag1−/− recipients of colitogenic CD4 T cells did not prevent induction of colonic inflammation." (PMID 29416538, 2018). "It was not surprising that the expression levels of CIDEC, NUMA1 and RAG1 in human subjects; Ndrg1 and Pea15a in mice with TNBS-induced colitis; and Cidec, Pea15a and Xbp1 in mice with DSS-induced colitis were not significantly different given the small sample sizes." (PMID 38778086, 2024). "Interestingly, the fact that DSS-induced colitis occurs even in SCID and Rag1−/− mice lacking T cells mediating adaptation indicates that innate immunity plays a pivotal role in this colitis model." (PMID 35457208, 2022). "To study whether adaptive immunity is required for development of colitis in the DSS model, we compared WT mice with RAG‐1−/− mice lacking B and T lymphocytes." (PMID 32567222, 2020). "RAG1 KO mice receiving LAG-3 KO responders + Treg displayed a generally intermediate phenotype, i.e. their colitis was less severe than those receiving no Treg at all, but slightly more severe (especially in terms of cell numbers) than mice receiving WT Treg and WT responders." (PMID 25372844, 2014).
Immunodeficiency (63 papers, 2009 to 2026). Failure of the immune system to protect the body adequately from infection, due to the absence or insufficiency of some component process or substance. "Mutations in 6 genes (IL12RB1, CYBB, IFNGR1, IL2RG, STAT1, and RAG1) account for 66% of BCG-associated immunodeficiency mutations." (PMID 41748971, 2026). "In mammals, deleterious RAG1 mutations have been shown to cause varying degrees of immunodeficiency, including T−B− severe combined immunodeficiency (SCID) and Omenn Syndrome53." (PMID 40592886, 2025). "Then, this study inspected published clinical cases with immunodeficiencies and found that 51.6% and 28.86% of patients with RAG1 and RAG2 mutations, correspondingly, had CpG methylation-mediated mutagenesis (p-value=0.0002)." (PMID 38240953, 2024). "A seven-month -old male baby who presented with persistent pneumonia and lymphopenia was found to have severe combined immune deficiency (SCID) due to a missense variant in the RAG1 gene." (PMID 39066397, 2024). "To examine this, we injected B7-H3 knockdown and control Tsc2-deficient 105K cells into wild-type and Rag1−/− mice, which have a combined T and B cell immunodeficiency." (PMID 36869048, 2023). "CRISPR/Cas9 system and somatic cell cloning technology were used to generate two pig models with FAH deficiency and exhibiting severe immunodeficiency (FAH/RAG1 and FAH/RAG1/IL2RG deficiency)." (PMID 35255981, 2022). "The Rag1 gene defect in humans is associated with a broad spectrum of clinical and immunological phenotypes and is one of the major causes of human immune deficiency (PID)." (PMID 34872353, 2021). "In this review, we will address several different challenges in the development of gene therapy for immune deficiencies using our own experience with Recombinase-activating gene 1 (RAG1) SCID as an example." (PMID 32545727, 2020). "In both thymoma and immunodeficiency caused by RAG1 or RAG2 mutations, thymic deficiency of AIRE has been documented." (PMID 29651287, 2018). "In this study, we analyzed inherited immunodeficiencies in four children, two girls and two related boys, caused by mutations in RAG1 gene." (PMID 28083621, 2016). "Importantly, we show that our yeast strains can effectively quantify the recombination efficiency of mutant RAG1 genes associated with immunodeficiency." (PMID 40592886, 2025). "Here, we showed that yeast cells expressing RAG1 variants with pathogenic mutations demonstrated a decreased level of recombination rate that correlated with disease severity, expanding the use of yeast models towards immunodeficiencies." (PMID 40592886, 2025). "As many of these mutations directly affect the ability of RAG1 to bind or cut DNA, we hypothesized that recombination rates seen in our assay would inversely correlate with the severity of RAG1-mutation-associated immunodeficiency." (PMID 40592886, 2025). "We then showed that our recombination platform could quantitatively predict deleterious mutations in RAG1, a common cause of various immunodeficiency disorders." (PMID 40592886, 2025). "In line with the NCBI data, 51.64% (110 out of 213) of the total number of mutations in cases with immunodeficiencies or autoimmunity had CpG mutations mediated by methylation in RAG1 coding sequence compared to 28.86% (28/97) in RAG2 coding sequence (z score = 3.74, p value = 0.0002)." (PMID 38240953, 2024). "Mutations in RAG1 have been reported to be associated with several types of immune disorders." (PMID 36732712, 2023). "Furthermore, given their prevalence in APS-1, RAG1/RAG2-associated immunodeficiencies, SLE, and now IPEX, it will be important to consider type I IFN ACAAs as potential diagnostics and biomarkers both in immunodeficiency and autoimmunity." (PMID 29651287, 2018). "Mutations in RAG1 gene may result in different types of severe combined immunodeficiencies." (PMID 28083621, 2016). "Rag1–/– mice are unable to generate mature T cells and B cells, leading to severe combined immunodeficiency." (PMID 38861331, 2024).
Immunodeficiency (continued). "Mutations in the recombination activating gene 1 (RAG1) and RAG2 in humans are associated with a broad spectrum of clinical phenotypes, from severe combined immunodeficiency to immune dysregulation." (PMID 37475856, 2023). "In summary, we have successfully generated IL2RG and RAG1 mutant monkeys with severe combined immunodeficiency using the CBE4max base editing system." (PMID 37661226, 2023). "As RAG1-SCID is a primary immunodeficiency, SIN lentiviral vectors were chosen for their ability to transduce HSCs and safety profile." (PMID 32545727, 2020). "Defects in RAG1/2 lead to a number of combined immune deficiencies including T-B- NK+ SCID, combined immunodeficiencies (CID) and more mild forms of immunodeficiencies including IgA deficiency." (PMID 32648006, 2020). "In summary, AK2 joins RAG1, ADA as well as ITCH and RMRP genes in the list of known causes of immune deficiency in the Amish population." (PMID 31673062, 2019). "We successfully generated TYR-KO, IL2RG-KO, and RAG1-KO Tibet minipigs, which are phenotypically characterized by albinism and/or immunodeficiency." (PMID 31754342, 2019). "An immunological disorder exemplifying this challenge occurs through damaging mutations in RAG1 and RAG2 which presents at an early age with a distinct phenotype of life-threatening immunodeficiency or autoimmunity." (PMID 31388879, 2019). "All cloned RAG1, RAG2, and IL2RG mutated piglets were raised in the conventional housing environment and piglets with immunodeficiency presented health issues." (PMID 31253764, 2019). "Hypomorphic RAG1 and RAG2 mutations, responsible for residual V(D)J recombination activity (on average 5–30%), result in a distinct phenotype of combined immunodeficiency with granuloma and/or autoimmunity (CID-G/A)." (PMID 31388879, 2019). "Pathogenic variants that severely impair recombinase activity of RAG1/2 determine a severe combined immunodeficiency (SCID) phenotype, whereas hypomorphic variants result in leaky (partial) SCID and other immunodeficiencies." (PMID 31058115, 2019). "RAG1 or RAG2 mutations are associated with defects in V(D)J recombination activity, causing severe immunodeficiency with a wide spectrum of clinical phenotypes." (PMID 30872621, 2019). "Adding to our knowledge of ACAAs in immunodeficiency, we recently discovered high titer type I IFN ACAAs in RAG1 and RAG2 mutation-associated immunodeficiencies." (PMID 29651287, 2018). "The MENA registry also reported high mortality in non-syndromic combined immunodeficiencies (51.7%) and syndromic CID (22.5%), particularly in patients with RFXANK, RAG1, and IL2RG mutations, where the most common causes of death were infection and respiratory failure." (PMID 40806973, 2025). "In this manner, we show in a non-vertebrate host cell the ability to study RAG1-associated immune deficiency and to generate in vivo combinatorial protein diversity via recombination of a predefined genetic locus." (PMID 40592886, 2025). "Indeed, RAG1 is involved in a severe spectrum of immunodeficiencies that can only be detected after birth (MIM:601457), while CSPP1 is involved in Joubert syndrome (MIM:615636) for which prenatal signs cannot be detected by US at early stages." (PMID 37035737, 2023). "In humans, mutations in RAG1 or RAG2 result in various degrees of residual V(D)J recombination activity, causing a broad spectrum of clinical phenotypes, ranging from severe combined immunodeficiency to autoimmunity." (PMID 36326898, 2022). "The other ones study the immune response more generally, using models displaying general immunodeficiency such as genetically modified SCID or RAG1-/- mice or animals immunosuppressed by the use of corticosteroids, the major iatrogenic risk factor of Pneumocystis pneumonia in humans." (PMID 35205883, 2022). "IL2RG-KO and RAG1-KO Tibet minipigs exhibited an apparent immunodeficiency phenotype." (PMID 31754342, 2019).
Immunodeficiency (continued). "RAG1 and RAG2 mutations in humans are associated with a broad spectrum of clinical and immunological phenotypes, including T− B− severe combined immune deficiency (SCID), Omenn syndrome (OS), atypical SCID (AS), and combined immune deficiency with granuloma and/or autoimmunity (CID-G/A)." (PMID 28769923, 2017). "Theseother defects have been considered as possible causes of the accelerated aging.However, immunodeficiency, alone, apparently is not the cause since micedeleted for Rag-1, also suffer from scid and chronic inflammation, but do notage prematurely." (PMID 19946467, 2009). "In addition, patients with abnormal RAG1 expression may develop severe immunodeficiency disorders, such as Omenn syndrome." (PMID 40920789, 2025). "Thus, it is possible that inhibition of RAG1 by small molecules could result in similar significant immunodeficiency or the development of autoreactive T cells, leading to autoimmune disorders." (PMID 39560443, 2024). "In conclusion, our work shows that GT could partially alleviate the combined immunodeficiency of hypomorphic RAG1 patients and that extensive efficacy and safety studies with alternative models are required before commencing RAG gene therapy in thesehighly complex patients." (PMID 38022635, 2023). "The IL2RG and RAG1-deficient monkeys described in this study hold value not only for oncology research but also represent a significant step forward in utilizing monkeys as models for severe immunodeficiency diseases in humans and regenerative medicine." (PMID 37661226, 2023). "Whole-exome sequencing (WES) identified a variation in RAG1 that may lead to immunodeficiency." (PMID 36732712, 2023). "In line with this, mice with severe combined immune deficiency (SCID) or recombination-activating gene 1 (RAG-1) gene deficiency (absence of B and T cells), demonstrated resistance to HTN, vascular abnormalities, renal damage, and water and salt retention, caused by Ang II or salt." (PMID 36176775, 2022). "Notably, although not required, the assay has been used across multiple pre-clinical studies of different gene therapy development for immunodeficiencies to assess the transforming potential of the newly developed lentiviral vectors such as X-linked SCID, Artemis SCID or RAG1 SCID." (PMID 32545727, 2020). "In summary, the RAG1-86nt hamster generated in this study could be used potentially as a model to study human immunodeficiency caused by mutations in the coding sequences for the non-core domain of RAG1, such as those identified in Omenn syndrome patients." (PMID 29734775, 2018). "The constructed FAH/RAG1/IL2RG triple-knockout pig models were characterized by chronic liver injury and severe immunodeficiency." (PMID 35255981, 2022). "The hub genes of this gene set were all critical genes involving the T cell signaling (LCK), antigen translocation (TAP1), and immunodeficiency diseases (JAK3 and RAG1)." (PMID 36180885, 2022). "In contrast to SCID mice, which develop some functional lymphocytes with age, the phenotype of Rag1−/− mice is described as a “non-leaky” immunodeficiency which makes this strain an ideal candidate for immune repopulation via bone marrow transplantation (BMT)." (PMID 35292674, 2022). "Additionally, RAG1 and RAG2 hypomorphic SCID models are also available, allowing to study gene therapy in a wider range of immunodeficiencies with one same strategy." (PMID 32545727, 2020). "Since no diagnostic details are given, the exclusion of combined immune deficiencies involving T-cell immunity as well as B-cell failure, or known mutations in monogenic disease (e.g. CTLA4, LRBA, KMT2D, XIAP, RAG1, NFKB1) is unclear." (PMID 33329602, 2020). "In parallel to the SIN lentiviral vector development, new vectors for immunodeficiencies not yet-treated, have started to be developed, such as for RAG1-SCID." (PMID 32545727, 2020).
Immunodeficiency (continued). "Unexpectedly, piglet d16 did not exhibit any symptoms of immunodeficiency, although genotype data revealed a 9 bp deletion in the RAG1 gene." (PMID 31754342, 2019). "The strong link to genetic defects (e.g., CYBB, RAG1 mutations) echoes findings in congenital immunodeficiency-associated IFI, suggesting that CA-IFI may warrant genetic testing even in the absence of classic immunodeficiency phenotypes." (PMID 40550072, 2025). "However, since Rag1 KO mice are immunodeficient, lacking B cells, T cells, and NKT cells, the possibility remained that some developmental abnormalities caused by the immunodeficiency might have secondarily led to the absence of IgG signals in the brain." (PMID 38750507, 2024). "To develop a Syrian hamster (Mesocricetus auratus) model of human immunodeficiency caused by RAG1 gene mutations, we employed the CRISPR/Cas9 system and introduced an 86-nucleotide frameshift deletion in the hamster RAG1 gene encoding part of the N-terminal non-core domain of RAG1." (PMID 29734775, 2018). "This study successfully achieved the generation of an immunodeficiency model in non-human primates by utilizing the CBE4max system to introduce specific single-nucleotide substitutions in the IL2RG and RAG1 genes." (PMID 37661226, 2023).
severe combined immunodeficiency (54 papers, 2008 to 2026). Severe combined immunodeficiency (SCID) comprises a group of rare monogenic primary immunodeficiency disorders characterized by a lack of functional peripheral T lymphocytes resulting in early-onset severe respiratory infections and failure to thrive. "ABOs reproduce the B cell developmental arrest observed in HSPCs from patients with RAG1-deficient severe combined immunodeficiency (SCID), which is corrected by a RAG1 gene therapy lentiviral vector." (PMID 42314684, 2026). "Recombinase-activating gene-1 (RAG1)-deficient severe combined immunodeficiency (SCID) patients lack B and T lymphocytes due to the inability to rearrange immunoglobulin and T cell receptor genes." (PMID 32322605, 2020). "Abnormalities in V(D)J recombination in individuals with combined immunodeficiency carrying hypomorphic RAG1 pathogenic variants show manifestations of autoimmunity." (PMID 29884787, 2018). "Loss-of-function of RAG1 due to nonsense mutations or gene knock-out abrogates T- and B-lymphocyte receptor formation prevents the maturation of T- and B-lymphocytes and leads to severe combined immunodeficiency (SCID; Schatz and Ji, 2011)." (PMID 34646823, 2021). "In this sense, rag1−/− zebrafish are comparable to the Rag1−/− severe combined immunodeficiency (SCID) mouse model, where mutations in multiple genes (including Rag1) create a deficiency in the functional adaptive immune system and a loss of B and T lymphocytes." (PMID 31348603, 2019). "Omenn syndrome (OS) is a rare autosomal recessive form of severe combined immunodeficiency (SCID) caused by mutations in the RAG1 or RAG2 genes." (PMID 39802943, 2025). "Genes commonly known to be associated with severe combined immunodeficiency (SCID), such as RAG1 and RAG2, are increasingly recognized among older adults with CID and autoimmunity." (PMID 35924244, 2022). "Severe combined immunodeficiency (SCID), caused by mutations in genes affecting lymphocyte development or function, such as IL-2RG, RAG1 and/or RAG2, and PRKDC, accounts for the most severe phenotypes among primary immunodeficient patients." (PMID 29593714, 2018). "Additionally, various companies managed to develop procedures to modify MN for use in genome editing to induce targeted recombination and correction of the RAG1 gene related to severe combined immunodeficiency (SCID) or XPC gene associated with xeroderma pigmentosum in skin cells." (PMID 29344676, 2018). "Mutations in recombinase activating gene (RAG1) cause various degrees of severe combined immunodeficiency syndrome (SCID).RAG1 is involved in the V(D)J recombination." (PMID 29067161, 2016). "In humans, mutations in RAG1 and RAG2 have been found in individuals with severe combined immunodeficiency (SCID), Omenn Syndrome, and combined immune deficiency with granulomas or autoimmunity (CID‐G/AI) (reviewed in 80)." (PMID 36939073, 2023). "However, unlike other IEI affecting B cell development resulting in agammaglobulinemia, variants in RAG1 or RAG2 cause severe combined immunodeficiency (SCID) because recombination of TCR chains during thymic development is also compromised." (PMID 37273190, 2023). "The mortality rate was the highest in patients with non-syndromic combined immunodeficiency (51.7%, median age: 3.5 years) and particularly in patients with mutations in specific genes associated with this phenotype (RFXANK, RAG1, and IL2RG)." (PMID 34052995, 2021). "Human islets were isolated and transplanted into either severe combined immunodeficiency (SCID) or recombination-activating gene 1 (RAG-1) immunodeficient recipient mice." (PMID 28735354, 2017). "Genetic defects in RAG1 and RAG2 are known to impair V(D)J recombination, thereby causing T-B-NK+ severe combined immunodeficiency." (PMID 26186701, 2015). "Loss of function mutations in the recombination activating genes RAG1 and RAG2 have been reported to cause a T-B-NK+ type of severe combined immunodeficiency." (PMID 26186701, 2015).